HECTD3 (HECT domain E3 ubiquitin protein ligase 3)
Diseases named in the same sentence as HECTD3 in open-access papers (continued):
Sharing a sentence is not in itself a finding about the gene and the disease.
tumor (11 papers, 2017 to 2026). "Taken together, we conclude that Hectd3 deficiency suppresses the inflammation-induced lung colonization of tumor cell." (PMID 35918322, 2022). "Here, we show that HECTD3 deficiency in ECs significantly reduces tumor metastasis in multiple mouse models." (PMID 35918322, 2022). "We show here that this domain, which is disrupted in the alternative spliced inactive isoforms found in CRAF-dependent tumor cell lines, is both necessary and sufficient for HECTD3 to associate with CRAF and with HSP90." (PMID 28636940, 2017). "To further confirm that Hectd3 deficiency inhibited tumor metastasis specifically through endothelial cells, we generated C57BL/6 strain Hectd3 floxed mice and crossed these mice with Tie2-Cre mice to obtain Tie2-Cre+;Hectd3fl/fl mice in which Hectd3 was specifically deleted in the endothelium." (PMID 35918322, 2022). "We next examined whether Hectd3 deficiency suppresses metastasis by downregulating adhesion molecule expression to inhibit tumor cell colonization in the lung." (PMID 35918322, 2022). "In addition, Hectd3 deficiency significantly prolonged mouse survival, demonstrating that Hectd3 deficiency in the tumor microenvironment inhibits surgery-associated tumor metastasis." (PMID 35918322, 2022). "In summary, our study revealed a previously unexplored connection between HECTD3 and two critical pathways of the tumor cell response to RT: DDR and autophagy." (PMID 39487119, 2024). "We found that 4T1-Luc2 tumor metastasis was markedly suppressed in Hectd3−/− mice (19%, 5/27), compared with that in WT mice (54%, 13/24)." (PMID 35918322, 2022). "First, we demonstrated that Hectd3 KO inhibited distant tumor relapse in spontaneous metastasis models in response to surgery or systemic inflammation." (PMID 35918322, 2022). "Second, HECTD3 depletion in HUVECs and mouse ECs blocked inflammation-induced adhesion molecule expression and tumor cell adhesion to ECs in vitro and in vivo." (PMID 35918322, 2022). "In summary, our data characterize the function of the HECTD3-IKKα axis in the adhesion of tumor cells to the endothelium through the NF-κB signaling pathway, which provides a potential strategy for tumor hematogenous metastasis prevention and treatment." (PMID 35918322, 2022). "Firstly, we detected several inflammation factors, such as LPS, TNFα, IL-1β and IL-6, in the sera of WT and Hectd3−/− mice burdening primary tumor (0 h) or surgically removed primary tumor 6 h or 12 h later." (PMID 35918322, 2022). "As shown at the beginning of this study, Hectd3−/− mice exhibited significantly decreased lung colonization of tumor cells which were intravenously injected into mice treated with LPS in advance." (PMID 35918322, 2022). "In this study, we provided evidence to support the notion that HECTD3 promotes tumor cell adhesion to ECs and metastasis by ubiquitinating IKKα in response to inflammation." (PMID 35918322, 2022). "It is warranted to develop small molecule inhibitors for HECTD3 and IKKα for tumor metastasis prevention, especially in patients who undergo surgical removal of the primary tumor." (PMID 35918322, 2022). "These animal experimental data confirm that Hectd3 promotes tumor metastasis by enhancing tumor cell colonization mediated by vascular endothelial cells in response to inflammation." (PMID 35918322, 2022). "Knockout of HECTD3 in endothelium significantly inhibits tumor cells lung colonization, while conditional knockin promotes that." (PMID 35918322, 2022). "HECTD3 promotes adhesion molecule expression by ubiquitinating IKKα, and Hectd3 KO inhibits tumor metastasis." (PMID 35918322, 2022). "As a result, the number of tumor cells infiltrated into WT mouse lung tissues is more than that into Hectd3−/− mouse lung tissues." (PMID 35918322, 2022). "We demonstrated that inhibition of the HECTD3-IKKα axis effectively inhibited tumor metastasis induced by systemic inflammation." (PMID 35918322, 2022).
tumor (continued). "HECTD3 associates with HSP90 and CRAF in cells via its N-terminal DOC domain, which is mutationally disrupted in tumor cells with activated MAP kinase signaling." (PMID 28636940, 2017). "Our data implicate HECTD3 as a tumor suppressor modulating the activity of this important oncogenic signaling pathway." (PMID 28636940, 2017). "In addition, Hectd3 conditional depletion in mECs inhibited tumor cell lung colonization in vivo, while Hectd3-specific overexpression in mECs increased that." (PMID 35918322, 2022). "However, the increase of lung colonization of tumor cell induced by LPS was significantly compromised in Hectd3−/− mice." (PMID 35918322, 2022). "HECTD3 may, therefore, have a tumor-suppressive function, controlling the amount of CRAF protein that can be activated through the HSP90 system and thereby limiting MAPK pathway activation." (PMID 28636940, 2017). "Finally, we inhibited expression of E-selectin, ICAM-1 and VCAM-1 using a siRNA mixture of siE-selectin, siICAM-1 and siVCAM-1, which blocked upregulation of expression of these adhesion molecules, as well as the increase in tumor cell adhesion induced by HECTD3 overexpression in HUVECs." (PMID 35918322, 2022). "Next, we assessed whether HECTD3 promotes the adhesion of tumor cells to HUVECs." (PMID 35918322, 2022). "Additionally, a group of E3 ubiquitin ligases, including HECTD3, MIB1 and FBW7 have been reported to inhibit tumor growth by targeting different ferroptosis related genes." (PMID 39557844, 2024). "HECTD3 depletion downregulates expression of adhesion molecules, such as VCAM-1, ICAM-1 and E-selectin, in mouse primary ECs and HUVECs stimulated by inflammatory factors and inhibits adhesion of tumor cells to ECs both in vitro and in vivo." (PMID 35918322, 2022). "Actually, the volume of 4T1-Luc2 primary tumor was larger in Hectd3−/− mice than in WT mice (Data not shown)." (PMID 35918322, 2022). "Currently, there are no effective HECTD3 inhibitors available, so we examined whether an IKKα inhibitor could suppress tumor metastasis." (PMID 35918322, 2022). "Full-length 97-kDa HECTD3 protein was readily detectable in HEK293 cells, but not in tumor cells." (PMID 28636940, 2017).
infection (3 papers, 2021 to 2026). The state of being infected such as from the introduction of a foreign agent such as serum, vaccine, antigenic substance or organism. "At the late stage of infection, the downregulation of HECTD3 enables the dimerization of PKR and thus suppresses virus replication while avoiding excessive inflammation." (PMID 37402711, 2023). "On the other hand, HECTD3-PKR mediated cell apoptosis may affect the propagation of RNA virus in the later stages of infection." (PMID 37402711, 2023). "By measuring the viral load on the cell surface or inside the cell at the early stage of infection, we found that HECTD3 did not affect the amount of the virus to adhere to or enter into macrophages." (PMID 37402711, 2023). "However, the role and the mechanism of HECTD3 in infection and inflammation have not been fully elucidated." (PMID 37402711, 2023). "Therefore, PKR might be the modified and regulated substrate for HECTD3 in the innate response to infection of RNA virus but not DNA virus." (PMID 37402711, 2023).
bacterial infection (2 papers, 2023 to 2024). "Recently, HECTD3 is implicated as an E3 ubiquitin ligase for TRAF3 and STAT1 in bacterial infection, hypothermic oxygenated perfusion of liver and cardiac inflammation models." (PMID 37402711, 2023). "HECTD3 has been reported to mediate the innate immune response to bacterial infection via promoting the ubiquitination of TRAF3, therefore one obvious question is whether TRAF3 is also the substrate of HECTD3 that mediates the anti-RNA virus response." (PMID 37402711, 2023).
infectious disease (1 paper, 2024). A disorder directly resulting from the presence and activity of a microbial, viral, or parasitic agent in humans. "HECTD3 is a E3 ubiquitin ligase of the HECT family that has been reported to participate in autoimmune and infectious diseases." (PMID 38267403, 2024).
liver (1 paper, 2021). "Further, western blot results showed that the expression levels of HECTD3 and TRAF3 in the IR group were significantly higher than those in the control group, suggesting that human liver IR during DCD liver transplantation promotes the expression of HECTD3 and TRAF3." (PMID 33627626, 2021). "Particularly, upon DCD liver IR insult, the DOC and HECT domains of HECTD3 directly bind to TRAF3, and the C832 of the HECT domain promotes the K63-linked polyubiquitination of TRAF3 at Lys138 to trigger oxidative stress and inflammatory response, thereby leading to serious liver IRI." (PMID 33627626, 2021).
HECTD3 also shares sentences with these, for which no sentence is quoted: Arthritis (1 paper); Autoimmunity (1); diabetes (1); hearing loss (1); heart failure (1); laryngeal squamous cell carcinoma (1); prostate carcinoma (1).